CDH6 (cadherin 6)
Description:
Cadherins are calcium-dependent cell adhesion proteins. They preferentially interact with themselves in a homophilic manner in connecting cells; cadherins may thus contribute to the sorting of heterogeneous cell types.
Synonyms: CAD6; KCAD
Tractability: Antibody: its Gene Ontology location is reachable by antibodies, with high confidence; UniProt places it where antibodies can reach, with medium confidence; UniProt predicts a signal peptide or a membrane-spanning region; the Human Protein Atlas places it where antibodies can reach. PROTAC: its protein half-life has been measured.
Gene: Protein-coding gene on chromosome 5 (31,193,686 to 31,329,146, forward strand). Ensembl gene ENSG00000113361.
Subcellular location: Cell membrane
Subcellular location (Human Protein Atlas): Cell Junctions; Plasma membrane
Pathways (Reactome):
Cell-Cell communication: Adherens junctions interactions
Gene Ontology:
Molecular function: beta-catenin binding; cadherin binding; calcium ion binding
Biological process: adherens junction organization; calcium-dependent cell-cell adhesion; cell adhesion; cell migration; cell morphogenesis; cell-cell adhesion mediated by cadherin; cell-cell junction assembly; synaptic membrane adhesion; cell-cell adhesion; homophilic cell-cell adhesion
Cellular component: cell junction; plasma membrane; adherens junction; catenin complex; glutamatergic synapse; membrane; synapse
Genetic constraint (gnomAD): Loss-of-function variants: 23 observed, 63.78 expected, observed/expected ratio (o/e) 0.36, 90% interval 0.26 to 0.51. The upper end of that interval is the gene's LOEUF score, 0.51, which puts it in group 2 of 6, group 1 being the genes least tolerant of losing a copy. Missense variants: 637 observed, 882.78 expected, observed/expected ratio (o/e) 0.72, 90% interval 0.68 to 0.77. Synonymous variants: 326 observed, 341.32 expected, observed/expected ratio (o/e) 0.96, 90% interval 0.87 to 1.05.
Homologues: Orthologues: chimpanzee CDH6 (99% identical), macaque CDH6 (99% identical), rabbit CDH6 (98% identical), rat Cdh6 (97% identical), pig CDH6 (97% identical), mouse Cdh6 (97% identical), guinea pig CDH6 (97% identical), dog CDH6 (95% identical), tropical clawed frog cdh6 (80% identical), zebrafish cdh6 (64% identical). Paralogues in human: CDH10 (73% identical), CDH9 (72% identical), CDH12 (61% identical), CDH7 (59% identical), CDH20 (59% identical), CDH8 (57% identical), CDH11 (57% identical), CDH18 (56% identical), CDH22 (50% identical), CDH24 (47% identical), CDH19 (46% identical), CDH5 (39% identical), and 21 more.
Diseases named in the same sentence as CDH6 in open-access papers:
CDH6 is named in the same sentence as 83 diseases in open-access papers, as found by Europe PMC text mining. Sharing a sentence is not in itself a finding about the gene and the disease. The quoted sentences say what the papers report.
ovarian carcinoma (21 papers, 2013 to 2025). A malignant neoplasm originating from the surface ovarian epithelium. "CDH6 has been associated with cancer cells in the literature as a target that is repressed by estrogen signaling in ovarian cancer." (PMID 27563818, 2016). "In addition to the association between CDH6 and a worse prognosis in ovarian serous carcinoma, αIIbβ3 associated with poor prognosis in clear‐cell and papillary renal carcinomas as well as in ovarian cancer." (PMID 33715292, 2021). "The in vitro antiproliferation data showed the CDH6-dependent cell killing activity by CUSP06 in ovarian cancer cell lines." (PMID 40871070, 2025). "Another emerging DXd-based ADC, raludotatug DXd (R-DXd, DS-6000a), targets cadherin-6 (CDH6) and is being evaluated in renal and ovarian cancers, where CDH6 expression is prevalent." (PMID 40650299, 2025). "The binding affinity of CUSP06 mAb and CUSP06 to endogenous human CDH6 was confirmed by a Fluorescence Activated Cell Sorting (FACS) method using CDH6-expressing human ovarian cancer cell line OVCAR-3." (PMID 40871070, 2025). "CUSP06 exhibited fast internalization kinetics in the two CDH6-expression ovarian cancer cell lines, PA-1 and OVCAR3, achieving 50% internalization between 1 and 4 h of treatment." (PMID 40871070, 2025). "These preclinical data support the therapeutic potential for CUSP06 in CDH6-low and CDH6-high ovarian cancer." (PMID 40871070, 2025). "CDH6 is expressed in cholangiocarcinoma, gastric cancer, renal cell carcinoma, ovarian cancer, and other cancers but less studied in pancreatic cancer, including ACC." (PMID 39410042, 2024). "Cadherin 6 (CDH6), highly expressed in renal cancer and ovarian cancer, interplays with αIIbβ3 via its RGD sequence, regulating tumor adhesion, migration and invasion." (PMID 36782235, 2023). "In ovarian cancer, there was a significant overexpression of CDH6 as compared to ovarian tissues, but αIIbβ3 expression remained constant." (PMID 33715292, 2021). "Two CDH6 isoforms were identified in ovarian cancer: the canonical full‐length (isoform 1) and isoform 2, which lacks the cytoplasmic tail." (PMID 33715292, 2021). "Silencing of α2 or αIIb inhibited the adhesive capacity of the ovarian cancer cells in the presence of CDH6 and CDH17 peptides." (PMID 33715292, 2021). "In ovarian cancer, Barx2 is expressed in the ovarian surface epithelium, where it induces the expression of cadherin 6, a functional suppressor of ovarian cancer progression." (PMID 27533254, 2016). "In spite of its role in promoting the epithelial phenotype during embryogenesis, CDH6 has been described as strongly expressed in ovarian cancer and renal carcinoma." (PMID 24069422, 2013). "This is in line with what has been reported in ovarian cancer and renal carcinomas, where an overexpression of CDH6 is observed in tumor cells as compared with the normal counterpart." (PMID 24069422, 2013). "CUSP06 demonstrated CDH6-dependent cytotoxicity in a panel of human ovarian cancer cell lines." (PMID 40871070, 2025). "Collectively, the preclinical pharmacology and toxicology data indicate CUSP06 could be an effective therapeutic to treat CDH6-positive human cancers, and a phase 1 study in ovarian cancer and other advanced solid tumors is ongoing (NCT06234423)." (PMID 40871070, 2025). "CUSP06 demonstrates CDH6-dependent cell killing activity in a panel of human ovarian cancer lines." (PMID 40871070, 2025). "CDH6 is also responsible for cellular adhesion and invasion in renal and ovarian cancers." (PMID 36352274, 2022). "In addition, CDH6 expression has been observed in ovarian carcinoma, thyroid cancers, cholangiocarcinoma, hepatocellular and small-cell lung carcinoma." (PMID 31324051, 2019). "In addition, RNA-seq data and tissue immunohistochemistry confirmed the restricted normal tissue distribution of CDH6 and the preferential expression in renal and ovarian cancers." (PMID 31324051, 2019).
ovarian carcinoma (continued). "This is the first time to our knowledge that a CDH6-targeted ADC has demonstrated antitumor efficacy in settings other than ovarian cancer and RCC and indicate CUSP06 could have therapeutic potential in CDH6-positive uterine cancer and cholangiocarcinoma patients." (PMID 40871070, 2025). "The in vivo antitumor activity of CUSP06 was investigated in three xenograft models in which CDH6 expression level are high: PA-1 (Ovarian Cancer), OVCAR-3 (Ovarian Cancer) and 786-O (Renal Cell Carcinoma)." (PMID 40871070, 2025). "The in vitro antiproliferative activity of CUSP06 was evaluated in two CDH6-expressing human ovarian cancer cell lines, OVCAR-3 and PA-1, and one CDH6 null ovarian cancer line ES-2." (PMID 40871070, 2025). "Cadherin-6 (CDH6) is a transmembrane protein expressed in many cancers, including epithelial ovarian cancers." (PMID 39590153, 2024). "Genes that contributed to the most variation between subtypes included known biomarkers and master regulators of ovarian cancer subtypes (MUC16 and PAX8) and many keratin and cadherin genes (KRT19, KRT7, KRT8, CDH6, and CDH1)." (PMID 39131380, 2024). "DS-6000a is a DXd-based ADC that targets the human cadherin 6 (CDH6), which is a transmembrane protein overexpressed in ovarian cancer and RCC." (PMID 36230766, 2022). "DS-6000a is an antibody–drug conjugate that binds to cadherin-6 (CDH6), which is overexpressed on the cell surface of RCC and ovarian carcinomas." (PMID 36551715, 2022). "So, mAbs 6.6.1 and 25.4.1 inhibited integrin activation induced by the CDH6 RGD motif, leading to the inhibition of pro‐metastatic activities and signaling pathways in both renal and ovarian cancer cells." (PMID 33715292, 2021). "HKT288, a first-generation anti-CDH6 ADC with a microtubule-targeting DM4 payload, has shown durable preclinical activity in 40% of patient-derived xenograft (PDX) models, especially those derived from ovarian cancer and renal cell carcinoma." (PMID 41164107, 2025). "Raludotatug deruxtecan (R-DXd), a CDH6-targeted ADC with the topoisomerase 1 inhibitor DXd, is currently in clinical trials for ovarian, renal and endometrial cancers, and exhibits promising clinical activity in ovarian cancer patients." (PMID 40871070, 2025). "In addition to PAX8, COPA complemented with pan-cancer analysis prioritized eight other lineage-restricted outliers (CDH6, CLDN16, FGF18, FOLR1, SLC34A2, SOX17, SPON1, WNT7A) displaying largely confined gene expression in ovarian cancer cell lines and tumor specimens." (PMID 31050342, 2019). "Raludotatug Deruxtecan (R-DXd), a CDH6-targeted ADC with the Topoisomerase 1 inhibitor DXd, is currently in clinical trials for advanced ovarian and renal cancers, and exhibits promising clinical activity in ovarian cancer patients without neurologic toxicities." (PMID 40871070, 2025).
thyroid cancer (17 papers, 2013 to 2025). "Follow-up work by Gugnoni and colleagues found that loss of CDH6 expression by siRNA attenuates the mesenchymal features of thyroid cancer cells by altering cytoskeletal architecture and intercellular associations." (PMID 35846375, 2022). "In thyroid cancer, CDH6 expression is strongly associated with EMT, metastatic behavior, and a worse disease outcome." (PMID 34530820, 2021). "Our results corroborated those of previous studies, indicating a significant role of CDH6 in breast and thyroid cancers and its correlation with Hippo and Wnt signaling pathways and stem cells." (PMID 35938030, 2022). "Regarding signaling, CDH6 was described as a TGF-β target gene in thyroid cancer cell lines to promote a mesenchymal phenotype." (PMID 31324051, 2019). "Another mesenchymal cell cadherin induced by TGFβ during the EMT is cadherin-6 (K-cadherin), which facilitates the invasiveness of thyroid cancer cells." (PMID 30463358, 2018). "Loss of CDH6 disrupted the cellular architecture and attenuated epithelial-to-mesenchymal transition (EMT) features of thyroid cancer cells." (PMID 30338239, 2018). "We recently found BNIP3 and BNIP3L (together with GABARAP) as CDH6 interactors in thyroid cancer cells." (PMID 27929542, 2016). "We show for the first time that CDH6 is expressed in human thyroid carcinomas and that its expression is enhanced at the invasive front of the tumor." (PMID 24069422, 2013). "CDH6 seems to be strongly expressed in aggressive thyroid carcinomas and nasopharyngeal carcinoma." (PMID 31324051, 2019). "Mila Gugnoni reported that cadherin-6 (CDH6) promotes the metastatic progression of thyroid cancer." (PMID 30338239, 2018). "In a parallel mechanism, thyroid epithelial cells undergoing EMT in response to TGFβ induce expression of cadherin-6 (also known as K-cadherin) and this cadherin is found expressed at high levels in aggressive thyroid carcinomas, thus classifying cadherin-6 as a TGFβ-inducible mesenchymal cadherin." (PMID 27367735, 2016). "CDH6 expression is restricted to a few normal adult human tissues including kidney, mammary gland and thymus; however, it is overexpressed in several human malignancies including ovarian, renal carcinoma, cholangiocarcinoma, thyroid cancers and uterine serous carcinoma." (PMID 40871070, 2025). "Notably, CDH6 expression is specific to thyroid cancer cells as compared to wild-type thyrocytes." (PMID 35846375, 2022). "Silencing cadherin-6 (CDH6) can inhibit EMT and invasiveness in thyroid cancer patients by promoting autophagy." (PMID 41030451, 2025). "The candidate NRGs were all highly expressed in thyroid cancer tissues, and candidate neoantigen genes, such as CDH6, ODZ1, and PROS1, were significantly differentially expressed in thyroid cancers." (PMID 37854594, 2023). "In the process of EMT, the silencing of the target gene Cadherin-6 of TGFβ can affect the EMT phenotype, activate of autophagy and inhibit the proliferation, migration and invasiveness of thyroid cancer cells." (PMID 36544104, 2022). "For example, by inhibiting autophagy, cadherin-6 facilitates epithelial mesenchymal transition (EMT) and cancer metastasis in thyroid cancer." (PMID 33381557, 2020). "In addition, CDH6 was reported to interact with autophagy-related proteins GABA Type A Receptor-Associated Protein (GABARAP), BCL2 Interacting Protein 3 (BNIP3) and BNIP3L to restrict autophagy and to promote the reorganization of the mitochondrial network in thyroid cancer cells." (PMID 31324051, 2019). "We showed that CDH6 silencing reverts the EMT phenotype by reducing proliferation and migration of thyroid cancer cells." (PMID 27929542, 2016). "We recently showed that TGFβ treatment in normal and thyroid cancer cell lines induces EMT through the activation of RUNX2 and its target CDH6.55, 56, 57 CDH6 silencing reverts the EMT phenotype and restrains migration and invasiveness in thyroid cancer cells." (PMID 27929542, 2016).
thyroid cancer (continued). "siRNA-mediated RUNX2 depletion impaired the positive transcriptional TGFβ effect on the expression of cadherin 6 (CDH6), whose product is a potential mesenchymal marker of the EMT program in thyroid cancer, controlling invasiveness of thyroid tumors." (PMID 26204939, 2015). "Cadherin 6 (CDH6), a TGFβ-target gene in the EMT process, is a major switch of the transition from the epithelial to the mesenchymal phenotype and a marker of metastatic potential in thyroid cancer." (PMID 27929542, 2016). "If this hypothesis is correct blocking the TGF-β signaling in thyroid cancer cells should affect RUNX2 and CDH6 expression levels." (PMID 24069422, 2013).
osteosarcoma (10 papers, 2019 to 2023). A usually aggressive malignant bone-forming mesenchymal neoplasm, predominantly affecting adolescents and young adults. "Regarding pediatric cancers, CDH6 overexpression was observed in osteosarcoma and was associated with the overall survival and prognosis of osteosarcoma patients, where CDH6 expression was regulated by miR-223-3p." (PMID 31324051, 2019). "Overexpression of CDH6 is closely associated with short OS in osteosarcoma patients." (PMID 34211976, 2021). "In osteosarcoma, CDH6 overexpression reportedly correlated with overall survival and patient prognosis." (PMID 35938030, 2022). "In human osteosarcoma, miR-223-3p functioned as a tumor suppressor to inhibit the metastasis and progression of osteosarcoma through regulating Cadherin-6 (CDH6)." (PMID 36276078, 2022). "For example, miR-223-3p repressed the metastasis and progression of osteosarcoma cells by targeting CDH6, over-expression of miR-223-3p suppressed the proliferation, invasion, and migration of breast cancer cells by targeting the ECT2 oncogene." (PMID 33522355, 2021). "Functional experiments suggest that miRNA can significantly inhibit the proliferation, invasion and migration of osteosarcoma cell lines through targeted regulation of CDH6." (PMID 34880371, 2021). "In vivo and in vitro studies have shown that miR-223-3p upregulation reduces osteosarcoma cell invasion, migration, growth, and proliferation by reducing CDH6 expression." (PMID 35154253, 2021). "CDH6 is a direct gene target of miR-223-3p and forced overexpression of miR-223-3p in cultured osteosarcoma cells reduces CDH6 expression and inhibits cell invasion and migration." (PMID 32600462, 2020).
glioma (8 papers, 2019 to 2025). A benign or malignant brain and spinal cord tumor that arises from glial cells (astrocytes, oligodendrocytes, ependymal cells). "In glioma, ridaforolimus is associated with elevated cadherin-6 (CDH6) expression in high-grade glioma patient-derived tumor cells." (PMID 38584599, 2024). "The significantly varying levels of expression in gliomas of different pathological grades indicate an underlying role of CDH6 in glioma genesis and progression." (PMID 35938030, 2022). "Its involvement in GWI is presently unknown but seems to be a candidate for further study because of its role in neuroinflammation; Cdh6, cahedrin 6, is associated with gliomas." (PMID 40606660, 2025). "Meanwhile, Notch1 pathway‐related genes, including Maml2, Ccn3, Fat4, Cdh6, and Ptp4a3, exhibited similar expression trends and may be intimately linked to glioma development." (PMID 39544152, 2024). "High expression of CDH6 is reported to correlate with tumor progression and poor prognosis in osteosarcoma, low-grade glioma and glioblastoma multiforme." (PMID 40871070, 2025). "Interestingly, it was observed that CDH6 is associated with immune infiltration and cytokine expression in glioma, suggesting that the CDH6 presence may facilitate the interaction between FLS and MLS, potentially contributing to the hyperplastic lining and chronic inflammation." (PMID 40877928, 2025). "Single-cell studies on the gene regulatory network and cell–cell communication are needed to clarify the role of CDH6 further in glioma malignancy and the microenvironment." (PMID 35938030, 2022). "To explore the role of CDH6 further in the glioma microenvironment, we evaluated the correlation between CDH6 and the commonly recognized immune cell markers." (PMID 35938030, 2022). "This study examined the cadherin-6 (CDH6) expression in gliomas using The Cancer Genome Atlas and Chinese Glioma Genome Atlas datasets." (PMID 35938030, 2022). "Hypomethylation of the CDH6 promoter potentially leads to high expression of CDH6 and poor prognosis in glioma patients." (PMID 35938030, 2022). "Gene Ontology and Kyoto Encyclopedia of Genes and Genomes enrichment analyses suggested that CDH6 might be involved in cell–cell interactions and immune processes in the glioma microenvironment." (PMID 35938030, 2022). "We examined CDH6 expression in five glioma single-cell datasets using TISCH." (PMID 35938030, 2022). "CDH6 positively correlated with CCR5, C‐C motif chemokine ligand (CCL) 5, IL12 receptor subunit beta 1, IL2 receptor gamma, IFN gamma receptor 2, and many other cytokines, indicating an important role of CDH6 in signal transmission and different immune processes in the glioma microenvironment." (PMID 35938030, 2022). "CDH6 levels in gliomas differed significantly in our collected samples." (PMID 35938030, 2022). "This indicates that CDH6 may play an essential role in glioma tumor progression and interactions with the microenvironment components." (PMID 35938030, 2022). "Thus, this study showed that CDH6 correlates with glioma immune infiltration, it is expressed mainly in AC-like malignant cells, and it may act as a new target for glioma therapy." (PMID 35938030, 2022). "In The Cancer Genome Atlas (TCGA) LGG–GBM and Chinese Glioma Genome Atlas (CGGA) 325 datasets, patients with low CDH6 expression showed a significantly longer overall survival than those with high CDH6 expression (p < 0.0001)." (PMID 35938030, 2022).